FOXM1 (forkhead box M1)
Diseases named in the same sentence as FOXM1 in open-access papers (continued):
Sharing a sentence is not in itself a finding about the gene and the disease.
gastric adenocarcinoma (2 papers, 2015 to 2018). "FOXM1 was shown to cause predominant nuclear staining in gastric adenocarcinomas, although some cytoplasmic staining was seen." (PMID 26576650, 2015). "FOXM1 expression was significantly associated with gastric adenocarcinoma (p = 0.001)." (PMID 26576650, 2015). "The expression levels of both PLK1 and FOXM1 mRNA are higher in gastric adenocarcinoma tissue compared to gastric tissue from healthy controls." (PMID 26576650, 2015). "This is suggestive of enhanced levels of FOXM1 protein in both dysplastic tissue and gastric adenocarcinomas (lanes 3 and 6)." (PMID 26576650, 2015). "We now show that there is also coordinate overexpression of FOXM1 and PLK1 in gastric adenocarcinomas, thereby providing the potential for feedback potentiation of FOXM1 activity." (PMID 26576650, 2015). "FOXM1 has previously been shown to be overexpressed in 88 % of gastric adenocarcinomas in a cohort of Chinese patients." (PMID 26576650, 2015). "Whilst our results suggest that both PLK1 and FOXM1 are implicated in carcinogenesis in gastric adenocarcinoma, blockade of one regulatory pathway is unlikely to halt cancer progression and induce widespread apoptosis in vivo." (PMID 26576650, 2015). "Moderate to high FOXM1 expression was significantly associated with gastric adenocarcinoma compared to non-cancer tissue (Mann–Whitney U p = 0.001)." (PMID 26576650, 2015). "In this study we have demonstrated that FOXM1 protein, and PLK1 and FOXM1 mRNA levels are all markers of gastric adenocarcinoma when compared to normal gastric tissue." (PMID 26576650, 2015). "This study has demonstrated that FOXM1 and its target gene PLK1 are coordinately overexpressed in a proportion of gastric adenocarcinomas." (PMID 26576650, 2015). "In the current study, we investigate the expression of FOXM1 and PLK1 in gastric adenocarcinomas with particular emphasis on examining whether there is evidence that FOXM1and PLK1 are co-ordinately expressed." (PMID 26576650, 2015). "FOXM1 expression did not have a correlation between survival or recurrence in gastric adenocarcinomas (data not shown)." (PMID 26576650, 2015). "We aimed to assess the expression of PLK1 and FOXM1 in Gastric adenocarcinomas in a Western Population, to examine whether there is a relationship of PLK1 to FOXM1 in cancer samples." (PMID 26576650, 2015).
hepatic (2 papers, 2016 to 2021). "Additionally, we found that the expression of Gli2, FoxM1 and KIF20A is significantly correlated with HBV-caused hepatitis, positive vascular invasion, poor histologic grade and TNM stage." (PMID 27036048, 2016). "Altogether, our findings provide insight into the pivotal involvement of FoxM1 in the tumor suppressive activities of Artemisinin and shed light on the potential application of Artemisinin for improved therapeutic response, especially in resistant hepatic malignancies." (PMID 34900697, 2021).
hilar cholangiocarcinoma (2 papers, 2018). A cholangiocarcinoma that arises from the junction, or adjacent to the junction, of the right and left hepatic ducts. "Specific a-disintegrin and metalloproteinase (ADAM) are overexpressed in many human cancers and related with poor clinical outcomes and tumor progression, silencing FoxM1 led to an inhibition of cell proliferation, tumor growth induced by ADAM-17 in hilar cholangiocarcinoma." (PMID 30580327, 2018).
Hypertension (2 papers, 2017 to 2022). The presence of chronic increased pressure in the systemic arterial system. "Dysfunctional ECs can induce FoxM1 expression in VSMCs and activate FoxM1-dependent VSMC proliferation, confirming ECs and VSMCs interaction through FoxM1 signaling in vascular remodeling and promoting hypertension and fibrosis." (PMID 35224067, 2022).
idiopathic pulmonary arterial hypertension (2 papers, 2024). A sporadic form of pulmonary arterial hypertension (PAH) characterized by elevated pulmonary arterial resistance leading to right heart failure. "BRD4 expression is elevated in patients with idiopathic pulmonary arterial hypertension (PAH) and promotes the upregulation of polo-like kinase 1 (PLK1) via forkhead box M1 (FoxM1)." (PMID 39215370, 2024).
Infertility (2 papers, 2019 to 2022). "On the other hand, NANOS3 and FOXM1 expression is enriched in human germ cells and a significant fraction of NANOS3 downregulated infertility (19/52) and cancer-germ cell genes (28/53) are also FOXM1 transcriptional targets (iRegulon)." (PMID 35743036, 2022). "These genes play important roles in cell proliferation (RFX4, FOXM1, ASF1B), differentiation during spermatogenesis (CATSPERG, SPDYA, SPATA16, TSACC, TCP10L, DPY19L2) and motility of sperm cells during fertilization (DNAAF1); mutations in these genes may lead to infertility." (PMID 31671693, 2019).
laryngeal carcinoma (2 papers, 2018 to 2024). Carcinoma that arises from the laryngeal epithelium. "FOXM1 overexpression has also been reported in several tumors, such as hepatocellular, pancreatic, colorectal and laryngeal cancer, with involvement in different mechanisms of oncogenesis, like cell proliferation, invasion, angiogenesis, and metastasis." (PMID 29682174, 2018). "NAT10‐mediated ac4C acetylation of FOXM1 promotes progression of laryngeal cancer." (PMID 39640362, 2024).
liposarcoma (2 papers, 2016 to 2019). A usually painless malignant tumor that arises from adipose tissue. "FOXM1 is elevated in de-differentiated liposarcoma and as FOXM1 is activated by progressive phosphorylation the relationship between palbociclib, CDK4 and FOXM1 in liposarcoma merits future research." (PMID 27074562, 2016). "Expectedly, YAP1 positivity was not restricted to MLS; however, nuclear expression of YAP1 was significantly more prevalent in MLS compared to other liposarcomas, and YAP1‐positive tumors showed strong expression of the YAP1 downstream targets FOXM1 and PLK1." (PMID 30898787, 2019).
metastatic prostate carcinoma (2 papers, 2007 to 2020). A carcinoma that arises from the prostate gland and has spread to other anatomic sites. "In addition, gene expression profiling in metastatic prostate cancer and in TNBC showed FOXM1 to be one of the top differentially expressed genes, with the potential to regulate many of the signaling pathways that control the hallmarks of cancer." (PMID 32961773, 2020).
neuroendocrine pulmonary tumors (2 papers, 2017 to 2019). "With most problems stemming from discriminating the subtypes of pulmonary neuroendocrine tumors, the combinations of FOXM1 with its downstream targets p27kip1 and p21waf1/cip1 may serve as an ancillary test to enhance diagnostic accuracy." (PMID 30992007, 2019).
progeria (2 papers, 2022 to 2025). "Also, in vivo cyclic induction of FOXM1 has been just recently disclosed as a safe strategy to extend healthspan in progeria and natural aging mouse models." (PMID 35835838, 2022).
prostate (2 papers, 2014 to 2020). "Recently, we established that prostate epithelial-specific expression of Foxm1 is required for prostate carcinogenesis." (PMID 25254494, 2014). "Overexpression of SETD1A was significantly correlated with overexpression of FOXM1 (GSE50936, GSE70769) and low survival rates of prostate patients (GSE40272)." (PMID 32629770, 2020).
rectal cancer (2 papers, 2022 to 2024). A primary or metastatic malignant neoplasm that affects the rectum. "Notably, in line with our findings, two independent groups demonstrated in gastric and colon rectal cancers that CSC have developed mechanisms for quenching excess ROS to maintain redox homeostasis including FOXM1-dependent Prx3 expression." (PMID 35241126, 2022).
serous carcinoma (2 papers, 2018 to 2021). "We also observed that FoxM1 overexpression is associated with high proliferative index (Ki67, p = 0.0072) in high grade serous carcinoma." (PMID 29423068, 2018). "FoxM1 over-expression was associated with adverse clinico-pathological parameters such as high grade serous carcinomas (p = 0.0221), poorly differentiated tumors (p = 0.0024) and high proliferative index (Ki-67, p = 0.0007)." (PMID 29423068, 2018). "Interestingly, only in high grade serous carcinoma FoxM1 overexpression showed significant association with elevated nuclear β-catenin expression (p = 0.0089)." (PMID 29423068, 2018). "OVCAR8 high-grade serous carcinoma cells were engineered for doxycycline (dox)-inducible FOXM1 and/or RHNO1 shRNA knockdown." (PMID 33890574, 2021). "We further analyzed the expression of FoxM1 in high grade serous carcinoma and low grade serous carcinoma." (PMID 29423068, 2018). "(B) Correlation of FOXM1 and RHNO1 promoter activity in Fallopian tube epithelium (FTE) (FT282) and high-grade serous carcinoma (HGSC) cell lines (OVCAR5, COV318, OVCAR4, Kuramochi, SNU119)." (PMID 33890574, 2021). "FOXM1 and RHNO1 each promote high-grade serous carcinoma cell clonogenic growth." (PMID 33890574, 2021).
testis cancer (2 papers, 2020 to 2022). "Taken together, we demonstrate the interplay between NANOS3, PUM1, and FOXM1 in regulating G2/M phase genes and disruption of this interplay in testicular cancer." (PMID 35743036, 2022). "A significant positive correlation, although moderate (0.65>R>0.35) between FOXM1 and pS345 Chk1, is observed in tumor samples from liver, ovarian, cervical and testicular cancer." (PMID 33253193, 2020). "Finally, we characterize FOXM1 as a target of NANOS3/PUM1 post-transcriptional repressor complex and elucidate the role of NANOS3-PUM1-FOXM1 axis in regulating G2/M phase cell cycle mRNAs, as well as its dysregulation in testis cancers." (PMID 35743036, 2022). "This analysis showed a much wider expression pattern for PUM1, NANOS3, FOXM1, and target cell cycle genes in testis cancer compared to healthy testis samples including altered NANOS3-FOXM1 and PUM1-FOXM1 correlations." (PMID 35743036, 2022).
thymic lymphoma (2 papers, 2019 to 2022).
tongue squamous cell carcinoma (2 papers, 2021). A squamous cell carcinoma that arises from the tongue. "Similarly, FOXM1 has been reported to exhibit high levels of expression in tongue squamous cell carcinoma, illustrated by its contribution to the stimulation of the migration and invasion capacities of SCC9 and SCC25 cells." (PMID 34447693, 2021).
undifferentiated pleomorphic sarcoma (2 papers, 2013 to 2016). An undifferentiated soft tissue sarcoma characterized by the presence of a pleomorphic malignant cellular infiltrate. "The RAS target FOXM1 was identified using this gene-set in human undifferentiated pleomorphic sarcoma." (PMID 24216705, 2013). "A suggested inference is that FOXM1 has a similar role in undifferentiated pleomorphic sarcoma." (PMID 27074562, 2016).
adrenocortical adenoma (1 paper, 2019). "FSCN1 and FOXM1 were over-expressed in ACC tissue when compared with adrenocortical adenoma and normal adrenal tissue." (PMID 31783819, 2019).
allergic asthma (1 paper, 2025). A asthma with a basis in a pathological type I hypersensitivity reaction. "The transcription factor FOXM1 has been shown to be a key regulator of epithelial proliferation and inflammation in allergic asthma." (PMID 40501685, 2025).
B-cell lymphoblastic leukemia (1 paper, 2019). "In another study, conditional knockdown of FOXM1 in precursor B-cell lymphoblastic leukemia cell lines was found to significantly prolong the survival of mice xenografted with leukemic cells." (PMID 31390744, 2019).
benign adenomas (1 paper, 2017). "We have demonstrated that FOXM1 is sufficient to drive progression of adenomas to adenocarcinomas and is required for maintainance of the mucinous phenotype." (PMID 29267283, 2017). "FOXM1 accelerated tumor growth, induced progression from benign adenomas to invasive, metastatic adenocarcinomas, and induced SOX2, a marker of poorly differentiated tumor cells." (PMID 29267283, 2017). "We have demonstrated that FOXM1 is sufficient to drive progression of adenomas to adenocarcinomas and is nessesary to maintain a mucinous phenotype." (PMID 29267283, 2017). "While the role of FOXM1 in lung tumor initiation and growth is well established, it is unclear whether FOXM1 enhances progression from adenomas to adenocarcinomas and regulates metastasis of lung tumors in vivo." (PMID 29267283, 2017).
benign breast tumour (1 paper, 2019). "Next, we analysed the expression level of Aurora‐A and FOXM1 in a panel of 66 TNBC samples and 11 benign breast tumour samples from GuangZhou First People’ hospital." (PMID 31359594, 2019).
bladder tumors (1 paper, 2018). "Up- and downstream FOXM1 regulators (e.g., FOXO3, PI3k, AKT) may be valuable drug targets and should be further explored also in bladder tumors." (PMID 29959570, 2018).
carcinomas of tongue (1 paper, 2021). "Moreover, FOXM1 can bind directly to the promoter of MET, which establishes, together with AKT, a positive feedback loop relevant not only to NSCLC but also to carcinomas of tongue and pancreas." (PMID 33660397, 2021).
cataract (1 paper, 2024). Partial or complete opacity of the crystalline lens of one or both eyes that decreases visual acuity and eventually results in blindness. "Furthermore, research has revealed that FOXM1 expression is elevated in the lens tissue of cataract patients, which results in TGF-β2 damaging human lens epithelial cells by boosting VEGFA production and initiating the MAPK signaling pathway." (PMID 38662949, 2024).
cerebral infarction (1 paper, 2025). An ischemic condition of the brain, producing a persistent focal neurological deficit in the area of distribution of the cerebral arteries. "Wnt-3a protein administration leads to Gsk3b dephosphorylation, reducing cerebral infarction and neuronal apoptosis through the Foxm1 pathway." (PMID 40529227, 2025).
cervical tumour (1 paper, 2021). "Several other studies have reported miR-214 to suppress cervical tumour growth and metastasis through targeting and downregulating high mobility group AT-hook 1 (HMGA1), Plexin-B1, Bcl2l2, Ezh2, and forkhead box protein M1 (FOXM1)." (PMID 34943783, 2021).
chronic kidney disease (1 paper, 2024). Impairment of the renal function secondary to chronic kidney damage persisting for three or more months. "Foxm1 deletion led to increased AKI to chronic kidney disease transition, with enhanced fibrosis and ongoing tubule injury 6 weeks after injury." (PMID 38916959, 2024).
dilated cardiomyopathy (1 paper, 2025). Cardiomyopathy which is characterized by dilation and contractile dysfunction of the left and right ventricles. "CM‐specific Foxm1‐knockout mice exhibit dilated cardiomyopathy features associated with mitochondrial dysfunction." (PMID 40546121, 2025).
ductal carcinoma in situ (1 paper, 2008). "In ductal carcinoma in situ of high grade type nuclear FOXM1 expression is slightly more intense (IRS = 2) than in normal breast tissue whereas the cytoplasmic FOXM1 expression is strong (IRS = 9)." (PMID 18254960, 2008).
emphysema (1 paper, 2015). "Moreover, the amount of FOXM1 protein was increased in bronchiolar epithelium and in inflammatory cells isolated from COPD patients, but no further studies were performed to investigate the role of FOXM1 in CS-induced emphysema in mice or humans." (PMID 25962837, 2015).
erythroplakia (1 paper, 2009). "Furthermore, our bioinformatics analysis based on a panel of microarray data showed that FOXM1 mRNA expression was significantly upregulated in both premalignant dysplastic lesions (leukoplakia and erythroplakia) and HNSCC compared to normal oral mucosa." (PMID 19287496, 2009).
gastritis (1 paper, 2024). Inflammation of the stomach. "In conclusion, this study demonstrated that thiopeptide-positive C. acnes has anti-inflammatory, antimicrobial, and anti-FOXM1 effects in vitro and in a GF mouse model of H. pylori gastritis." (PMID 38014984, 2024).
glaucoma (1 paper, 2023). Increased pressure in the eyeball due to obstruction of the outflow of aqueous humor. "Prioritized gene variants in our glaucoma case-control cohort supported possible causal roles in four genes for POAG (AQP5, FOXM1, SRFBP1 and CDH6) and three genes in PACG (LAMA2, ACACB and RGL3)." (PMID 36833422, 2023). "Rare, deleterious SNVs in AQP5, SRFBP1, CDH6 and FOXM1 from POAG families and in ACACB, RGL3 and LAMA2 from PACG families were found exclusively in glaucoma cases." (PMID 36833422, 2023). "We identified rare, possibly pathogenic variations in AQP5, FOXM1, SRFBP1 and ACACB in the sporadic glaucoma cases that were not present in the families." (PMID 36833422, 2023).
gynecologic cancer (1 paper, 2014). "To assess the potential of FoxM1 as a therapeutic target, we treated gynecologic cancer cell lines with FoxM1 inhibitor, thiostrepton." (PMID 25426548, 2014).
Hydrocephalus (1 paper, 2023). Hydrocephalus is an active distension of the ventricular system of the brain resulting from inadequate passage of CSF from its point of production within the cerebral ventricles to its point of absorption into the systemic circulation. "In hydrocephalus, trans-regulation encompasses several lncRNAs involved in pathways regulated by the transcription factor FOXM1." (PMID 37238726, 2023).
hypopharyngeal squamous cell carcinoma (1 paper, 2021). "The overexpression of FOXM1 has been shown to promote cell proliferation and migration while acting to inhibit the apoptosis of hypopharyngeal squamous cell carcinoma, ultimately contributing to poor clinical prognosis." (PMID 34447693, 2021).
immunodeficiency disorders (1 paper, 2014). "Developing a thorough understanding of the regulation and function of FOXM1 in DNA damage response will improve the diagnosis and treatment of diseases including cancer, neurodegenerative conditions and immunodeficiency disorders." (PMID 25287128, 2014).
infarction (1 paper, 2019). A localised pathological necrosis of tissue resulting from obstruction of the blood supply usually by a thrombus, an embolus, or vascular torsion. "Consisted with the echocardiography data, the histology assay showed significant reduction of infarction size in Foxm1 overexpression group (65.90 ± 5.33%) compared with Luc group (42.92 ± 3.23%) at day 28 after MI." (PMID 30552062, 2019). "The Luc group showed an average EF of 27 ± 3% and FS of 11 ± 1% 28 days after MI, while Foxm1 overexpression significantly prevented the infarction progress and maintained the cardiac function with an average EF of 36 ± 2% and FS of 16 ± 1%." (PMID 30552062, 2019).
intraepithelial neoplasia (1 paper, 2025). A precancerous neoplastic process that affects the squamous, glandular, or transitional cell epithelium without evidence of invasion. "The IHC method was carried out to observe whether there were differences in the expressions of UBE2S, HIF‐1α, and FOXM1 in low‐grade intraepithelial neoplasia (LIN), high‐grade intraepithelial neoplasia (HIN), and the normal epithelial tissues of the esophagus." (PMID 41427004, 2025).
ischemic stroke (1 paper, 2025). A stroke disorder caused by obstruction of blood flow to the brain, due to thrombotic (local blood clot formation) or embolic (due to a blood clot or other material traveling from another site) event. "Together, our results highlight the therapeutic potential of hAECs-Exos as a safe, effective, and clinically translatable strategy for ischemic stroke treatment, warranting future validation in vivo and rescue experiments to fully elucidate FoxM1’s causal role." (PMID 41154771, 2025). "The role of FoxM1 in regulating neuroprotection following ischemic stroke remains to be thoroughly investigated in animal models that recapitulate the complex neurovascular environment of the brain." (PMID 41154771, 2025). "FoxM1 stands out as a novel focus in ischemic stroke research because of its ability to integrate multiple pathological pathways, which stands in sharp contrast to other transcription factors previously studied in stroke models." (PMID 41154771, 2025).